IL6 (interleukin 6)
Diseases named in the same sentence as IL6 in open-access papers (continued):
Sharing a sentence is not in itself a finding about the gene and the disease.
Salmonella Infections (continued). "PJ-34, a potent poly (ADP-ribose) polymerase-1 (PARP-1) inhibitor, may exert defense on intestinal epithelial cells (IECs) against invasive Salmonella infection by up-regulating IL-6 production through the ERK and NF-κB signal pathway." (PMID 34943999, 2021). "For example, pregnant mice which rapidly succumbed to normally innocuous Salmonella infection were shown to have increased serum IL-6 levels, as well as blunted migration of leukocytes to infected target organs, whereas pregnancy-induced Salmonella susceptibility was reversed with IL-6 blockade." (PMID 33622714, 2021). "During invasive Salmonella infection, pattern recognition receptors initiate the innate immune system leading to the recruitment of neutrophils and macrophages and the production of proinflammatory cytokines (IL-6, IL-1β) to promote pathogen clearance." (PMID 32842467, 2020). "Moreover, in a Salmonella infection model in rabbits the IL6 levels were significantly reduced after a combined treatment with antibiotics and Pep19-2.526." (PMID 32346013, 2020). "In addition, VDR-/- mice had an increased bacterial burden and mortality, more easily detectable levels of IL-6 and elevated NF-κB activity in intestinal epithelia after Salmonella infection." (PMID 26172950, 2015). "In addition, cytokine mRNA levels (Il1, and Il6) known to be upregulated during Salmonella infection and to impact on Hamp transcription were measured." (PMID 23390527, 2013). "Although we focused our analysis on IFN-γ, IL-6 and IL-10 may also be important mediators of the mucosal responses to Salmonella infection." (PMID 22624013, 2012). "In conclusion, the present study provides the first evidence that PJ-34 may enhance IL-6 production in enterocytes subjected to Salmonella infection and that the effect of PJ-34 is, at least in part, through NF-κB and ERK signal pathways." (PMID 20204057, 2009). "As reported by others, Salmonella infection significantly increased expression of IL-6 and IL-8." (PMID 19589170, 2009). "The initial stages of Salmonella infection are characterized by effective recruitment and activation of phagocytes, partly due to a massive inflammatory response in infected tissues, including the expression of inflammatory cytokines [e.g., IL-6, IL-12, and IL-18]." (PMID 36361621, 2022). "In addition, IL-6 indirectly regulates the IFN-γ in the pathway of Salmonella infection." (PMID 28659929, 2017). "IL-6 and IL-10 gene expression are also significantly increased in infected p19−/− mice, and these cytokines may contribute to host defense and mucosal tissue injury against Salmonella infection in p19−/−." (PMID 22624013, 2012). "Salmonella infection robustly induces proinflammatory cytokines, including tumor necrosis factor (TNF-α) and interleukin 6 (IL-6), and triggers caspase-1-dependent proinflammatory programmed cell death (8, –, 10)." (PMID 35579463, 2022). "Comparatively, when compared to WT mice, TNF-α, IL-6, and INF-γ of MafK Tg mice were increased significantly following Salmonella infection for 2 days in the colon." (PMID 35260530, 2022). "The results revealed that Salmonella infection up-regulated all studied pro-inflammatory cytokines such as TNF-α, IL-8, IL-6 and TLR4, TLR5 signaling pathways, while decreasing the expression of TGF-β." (PMID 36556320, 2022). "When administered in adequate amounts, probiotics have the ability to modulate the expression of immune-related cytokines, including interleukins IL4, IL6, IL12, IFN-γ, and IL1β in lymphoid cells during Salmonella infection." (PMID 33897683, 2021). "Two genes, IL6 and DGKA, overlapped between the potential targets in Pingwei Pill, colistin, and the known therapeutic targets for Salmonella infection." (PMID 34663394, 2021). "Taken together, our results established that Pingwei Pill is the potential candidate for Salmonella infection by targeting MCR-1, IL6 and DGKA genes to recover the colisitn activity, and inhibit the bacteria adhesion and invasion." (PMID 34663394, 2021).
Salmonella Infections (continued). "IL6 and DGKA were another two key targets between Pingwei Pill and colistin, the two genes were also Salmonella infection related genes, which mainly played a role of focal adherents, bacterial invasion of epithelial cells and chemokine signaling pathway." (PMID 34663394, 2021). "There had been an interaction between heat stress and Salmonella infection in the expressions of TNF-α, IL-6, IL-1β, pro-IL-1β, and NLRP3." (PMID 34061266, 2021). "Many studies have indicated that the expression of proinflammatory cytokines such as IFN-γ, IL-6, IL-1β, LITAF, and anti-inflammatory cytokines (IL-10 and transforming growth factor-β4) is regulated in the cecal tonsils by Salmonella infection." (PMID 32054193, 2020). "Epithelial STAT3 activation seems to promote Salmonella infection (bottom), which suggests that enforced production of the STAT3 inducer IL-6 serves Salmonella to propel the establishment of its infection niche." (PMID 32071273, 2020). "Although the detailed mechanism of miR-146a regulation of IFN-γ and IL-6, and the establishment of different shedding status, remains unknown, it is clear that an appropriate innate immune response is required to defend an organism against Salmonella infection." (PMID 31186019, 2019). "Salmonella infection (SAL group) significantly increased the levels of LITAF, IL-1β, and IL-6 in serum compared with the NC group (P < 0.05)." (PMID 29396554, 2018). "Let-7 was down-regulated to induce the release of cytokine IL6 (interleukin 6) and IL10 to participate in the regulation of immune response to Salmonella infection in macrophages." (PMID 28086873, 2017). "Instead, genes such as IL1β, IL6 or both chicken orthologues of IL8 (EMF-1 and K60), which are commonly used as markers of inflammation following Salmonella infection of chickens were inducible also in fibroblasts." (PMID 26046914, 2015). "The preincubation of DCs with LP-treated-EC supernatants prior to Salmonella infection, drastically reduced the DC's ability to activate T cells and drive their polarization to Th1 T cells as evidenced by a decrease in IFN-γ, IL-2 and IL-6 production." (PMID 19756155, 2009). "Compared to the CON, clove extract and eugenol notably reduced the expression levels of pro-inflammatory cytokines IL-1β, IL-6, and TNF-α in the jejunal tissue and crypts of yellow feather broilers; Salmonella infection significantly elevated the levels of these inflammatory factors." (PMID 40059168, 2025). "Contrary to our expectation, Salmonella infection was also enriched in clusters 1 and 3, and thus, we reviewed the DEGs and found that only six DEGs, such as AHNAK, MAP2K1, MAPK10, ARL8B, IL6, and PFN2, were enriched after S. enterica BNCC186354 infection, but only ARL8B and PFN2 were downregulated." (PMID 36980306, 2023). "Enhanced iNOS activation, NO production, and IL-6 expression were also observed in the absence of SLAMF8 upon Salmonella infection, either in vivo or in vitro, while overexpression of SLAMF8 in RAW264.7 macrophages showed the opposite phenotype." (PMID 35837407, 2022). "So Pingwei Pill might combine with colistin act on the IL6 and DGKA targets to inhibit Salmonella infection such as restoring the damaged intestinal epithelial surface, decrease cytokines level." (PMID 34663394, 2021). "It suggests that PJ-34 may exert its protective effect on intestinal epithelial cells against invasive Salmonella infection by up-regulating IL-6 production through ERK and NF-κB but not P38 MAPK, JNK or PI3K/Akt signal pathways." (PMID 20204057, 2009). "As observed for AIEC-LF82, in case of Salmonella infection the absence of either ELMO1 or NOD2 or both resulted in a delayed bacterial clearance and significant decline in levels of IL-6 and IL-1β compared to C1 cells." (PMID 36694274, 2023).
rheumatic diseases (77 papers, 2009 to 2025). "Interleukin-6 (IL-6) is a multiple-effect cell factor implicated in the etiopathogenesis of several rheumatologic disorders." (PMID 38835791, 2024). "In contrast, successful therapeutic approaches for various rheumatic diseases by targeting the IL-6 pathway underlines the importance of IL-6 in bone metabolism." (PMID 35812457, 2022). "Passive immunization aimed at neutralizing the pathogenic cytokines such as TNF-α and IL-6 with monoclonal antibodies (mAbs) or soluble receptors has been proven to be an effective therapy strategy of rheumatic diseases such as RA and AS." (PMID 32258176, 2020). "Interleukin 6 (IL-6) is a pro-inflammatory cytokine implicated in several rheumatic diseases and in the so-called cytokine release syndrome (CRS)." (PMID 33087150, 2020). "Withholding live-attenuated vaccines in patients using interleukin (IL)-1 or IL-6 blocking agents is recommended by guidelines for both pediatric and adult rheumatic diseases, since there is a risk of infection in an immune suppressed host." (PMID 29562920, 2018). "Stress cytokines tumor necrosis factor α, interleukin-1 β and interleukin-6 modulate the activity of a variety of cell types including osteoblasts, and are involved in the pathogenesis of several rheumatic diseases associated with systemic bone loss." (PMID 23675187, 2010). "This monoclonal antibody, which binds to interleukin 6 (IL-6) receptor and blocks the IL-6 mediated inflammatory response, is approved for treatment of rheumatologic disorders and cytokine-release syndrome associated with Chimeric Antigen Receptor T-cell (CAR-T) administration." (PMID 32817707, 2020). "Proinflammatory cytokines, including tumor necrosis factor-alpha (TNF-α), interleukin-6 (IL-6), and interleukin-17 (IL-17), are elevated in rheumatic disorders due to persistent inflammation." (PMID 40937212, 2025). "IL-6 and TNF-α are central cytokines in chronic low-grade inflammation and have been linked to functional decline and frailty in rheumatic diseases." (PMID 41488632, 2025). "Excessive production of IL-6 is characteristic of many rheumatic diseases, including Rheumatoid Arthritis, Juvenile Idiopathic Arthritis, and Adult-Onset Still’s Disease." (PMID 39229261, 2024). "Proinflammatory cytokines such as TNFα (tumor necrosis factor alpha), IL-6 (interleukin 6) and IL-1β (interleukin 1 beta), which circulate in the systemic blood flow in rheumatic diseases, influence the brain structures." (PMID 39845811, 2024). "The IL6 antagonists are indicated in the treatment of rheumatological disorders and in patients with cytokine release syndrome, occurring as an adverse effect of chimeric antigen receptor T cell therapy." (PMID 38667300, 2024). "It is evident that several rheumatic diseases display elevated serum levels of inflammatory cytokines, such as IL-2, IL-6, TNF-α and markers of systemic inflammation." (PMID 37681925, 2023). "Methotrexate plays an important role as an anti-inflammatory drug in rheumatic diseases by inhibiting IL-1 and IL-6." (PMID 36365080, 2022). "IL6 is a pleiotropic cytokine with numerous biological functions, which is involved in the pathogenesis of a variety of rheumatic diseases." (PMID 35342751, 2022). "As a pleiotropic cytokine with multiple biological functions, IL-6 participates in the pathogenesis of various rheumatic disorders." (PMID 36588535, 2022). "Pathogenic cytokines such as TNF-α, interferon-α (IFN-α), and interleukin-6 (IL-6) are critical mediators of autoimmune damages to host cells and tissues and have long been regarded as therapeutic targets for rheumatic diseases." (PMID 32258176, 2020). "Exercise also inhibited TNF expression in rheumatic diseases by stimulating muscle production of interleukin-6 (IL-6) and by promoting the production of interleukin-1 receptor antagonist (IL-1Ra), and interleukin-10 (IL-10)." (PMID 31681001, 2019).
rheumatic diseases (continued). "The cytokine IL-6 is one of the most prominent mediators in septic patients but also in patients with rheumatism." (PMID 25893429, 2015). "The change in cytokine levels elicited by stress in patients with rheumatic disorders was small or inconsistent, for example, for the most frequently measured cytokine IL-6." (PMID 20478029, 2010). "In rheumatic disorders, individualized cardiovascular risk management is made possible by combining inflammation-sensitive methods like CAC score, biomarkers (such as hs-CRP and IL-6), and sophisticated imaging." (PMID 40937212, 2025). "Since antibody-based therapeutics that either bind directly to IL-6 or block the effect of IL-6 by binding to its receptor are already in use for inflammatory and rheumatologic disorders, several clinical trials have tested this approach (NCT04333706, NCT04940299, and NCT02644967)." (PMID 38611065, 2024). "IL-6 is the second most important inflammatory cytokine in rheumatic diseases, and levels of IL-6 are higher in patients with AS than in controls, especially in the early stages of the disease, in serum, cartilage, synovial fluid and sacroiliac joint biopsy specimens." (PMID 38054001, 2023). "She started IL-6 inhibitor 2 months before the onset of empyema because her rheumatism worsened." (PMID 35389108, 2022). "Studies showing that injection of some of the key cytokines produced in rheumatic diseases into HC, such as IL-1β or IL-6, produces fatigue and that biologics targeting IL-6 or TNF-α ameliorate fatigue suggest a role for these molecules in the development of fatigue." (PMID 31685018, 2019). "The aim of this observational, prospective, pilot study was to investigate whether salivary concentrations of CRP and IL-6 correlate with those in serum and with the clinical course of a rheumatic disease." (PMID 30043213, 2018). "Increased serum levels of many cytokines were indeed found in other rheumatic diseases: notably psoriatic arthritis (IL-6, IL-7, IL-10, and IFN-γ, TGF-β, or TNF-α) suggesting that such rises may reflect inflammation rather than being disease specific." (PMID 28057980, 2016). "However, the decrease of serum in IL-6 and IL-17 observed in the present study might support a possible role of vitamin D supplementation in patients suffering from rheumatic diseases, in which IL-6 and IL-17 are key players in their pathogenesis." (PMID 36432510, 2022). "However, ANAs may be present in healthy subjects and patients with a variety of diseases, including non-rheumatic diseases, and their level may be increased by IL-6." (PMID 23432807, 2013). "In synovial cell cultures derived from patients with rheumatic diseases, IGU significantly reduced the production of IL-6, IL-8, and colony-stimulating factors." (PMID 39449973, 2024). "For example, there is a group of cytokines, including IL-1, IL-6, and TNF-α, for which the functions have been fully described by many researchers, especially regarding their role in rheumatic diseases." (PMID 38255240, 2024). "In this line, several studies have revealed that curcuminoids act to inhibit the expression of IL-1, IL-8, and IL-6, and TNF-α, thereby decreasing the severity of rheumatic disease." (PMID 37521415, 2023). "Our findings agree with previous reports that IL-6 and IDO in ADSCs from patients with rheumatic diseases; however, the results of TSG-6 and PGE2 are inconsistent and the results of TSG-6 are contradictory." (PMID 35252190, 2022). "Marked increase of proinflammatory cytokines including IL-1, IL-6, IL-18, TNFα, IFNγ, ferritin and ST2 during MAS attacks portrayed a significant systemic inflammation in patients with various rheumatic diseases, particularly sJIA28,44–47." (PMID 34099791, 2021). "Adiponectin the second adipokine most evaluated in rheumatic diseases possesses a complex role with some anti-inflammatory effects as well as inhibition of TNF-α and IL-6 production and the induction of IL-10 synthesis." (PMID 28898254, 2017).
rheumatic diseases (continued). "In order to confirm the potential impact of circulating IL-6 for plasma-NGAL levels found in septic patients and patients with rheumatic disease after treatment with an anti-TNF agent, whole blood samples were stimulated with IL-6." (PMID 25893429, 2015). "Our previous study documented that blood serum IL-6 levels do not differ significantly between PsA and RA, and IL-6 cannot be used as a marker differentiating these rheumatic diseases." (PMID 39684771, 2024). "For example, IL-37, a member of the IL-1 family which is stimulated by SARS-CoV-2, has been shown to suppress IL-1β, IL-6, TNFα and CCL2 in rheumatic diseases by acting on mTOR and enhancing the AMPK activity, to maintain mitochondrial membrane potential and limit the toxic effects of ROS." (PMID 36389723, 2022). "Moreover, critical proinflammatory cytokines such as IL-6, C-reactive protein (CRP), and tumor necrosis factor (TNF-α) not only play a pivotal role in the inflammatory cascade and evolution of rheumatic diseases but also are independent predictors of CVD." (PMID 34504395, 2021). "In conclusion, salivary concentrations of CRP, but not of IL-6, in patients with rheumatic disease significantly decrease over the course of successful anti-TNFα therapy and parallel changes in the disease activity." (PMID 30043213, 2018). "Despite the paucity of in vivo studies, this comprehensive review suggests that O2O3 therapy might reduce serum levels of interleukin 6 in patients with TMD, low back pain, knee osteoarthritis and rheumatic diseases with a concrete and measurable interaction with the inflammatory pathway." (PMID 35269681, 2022). "Thus, lower serum IL-6 level in DM than in RA, SLE, and SS may be an explanation to the differences in autoantibody production in these rheumatic diseases." (PMID 24082909, 2013). "Salivary CRP but not IL-6 could be of potential use for monitoring the rheumatic disease activity." (PMID 30043213, 2018). "IL-6 is not used routinely in the follow-up of SLE patients but its role in inflammation it is widely known generally and in rheumatic diseases in particular." (PMID 38474267, 2024).